MRAP2 (melanocortin 2 receptor accessory protein 2)
Description:
Modulator of melanocortin receptor 4 (MC4R), a receptor involved in energy homeostasis. Plays a central role in the control of energy homeostasis and body weight regulation by increasing ligand-sensitivity of MC4R and MC4R-mediated generation of cAMP (By similarity). May also act as a negative regulator of MC2R: competes with MRAP for binding to MC2R and impairs the binding of corticotropin (ACTH) to MC2R. May also regulate activity of other melanocortin receptors (MC1R, MC3R and MC5R); however, additional evidence is required in vivo.
Synonyms: C6orf117; bA51G5.2
Tractability: Antibody: UniProt places it where antibodies can reach, with high confidence; its Gene Ontology location is reachable by antibodies, with high confidence; UniProt predicts a signal peptide or a membrane-spanning region.
Gene: Protein-coding gene on chromosome 6 (84,033,203 to 84,090,887, forward strand). Ensembl gene ENSG00000135324.
Subcellular location: Cell membrane; Endoplasmic reticulum membrane
Gene Ontology:
Molecular function: corticotropin hormone receptor binding; identical protein binding; protein binding; type 1 melanocortin receptor binding; type 3 melanocortin receptor binding; type 4 melanocortin receptor binding; type 5 melanocortin receptor binding; signaling receptor regulator activity
Biological process: negative regulation of adenylate cyclase-activating G protein-coupled receptor signaling pathway; negative regulation of protein localization to plasma membrane; positive regulation of adenylate cyclase-activating G protein-coupled receptor signaling pathway; protein localization to plasma membrane; energy homeostasis; energy reserve metabolic process; feeding behavior; regulation of adenylate cyclase-activating G protein-coupled receptor signaling pathway
Cellular component: endoplasmic reticulum; plasma membrane; endoplasmic reticulum membrane
Genetic constraint (gnomAD): Loss-of-function variants: 20 observed, 18.36 expected, observed/expected ratio (o/e) 1.09, 90% interval 0.76 to 1.58. The upper end of that interval is the gene's LOEUF score, 1.58, which puts it in group 6 of 6, group 1 being the genes least tolerant of losing a copy. Missense variants: 238 observed, 253.13 expected, observed/expected ratio (o/e) 0.94, 90% interval 0.85 to 1.05. Synonymous variants: 96 observed, 93.62 expected, observed/expected ratio (o/e) 1.03, 90% interval 0.87 to 1.22.
Homologues: Orthologues: chimpanzee MRAP2 (99% identical), dog MRAP2 (94% identical), pig MRAP2 (93% identical), rabbit MRAP2 (93% identical), guinea pig MRAP2 (92% identical), rat Mrap2 (89% identical), mouse Mrap2 (88% identical), tropical clawed frog mrap2 (62% identical), zebrafish mrap2a (47% identical).
Diseases named in the same sentence as MRAP2 in open-access papers:
MRAP2 is named in the same sentence as 12 diseases in open-access papers, as found by Europe PMC text mining. Sharing a sentence is not in itself a finding about the gene and the disease. The quoted sentences say what the papers report.
Obesity (62 papers, 2014 to 2026). Accumulation of substantial excess body fat. "This aligns with previous study showing that rare MRAP2 variants are associated with higher BMI and obesity risk in both adults and children." (PMID 41596694, 2026). "In total, 27 rare coding MRAP2 variants were observed in 46 (1.01%) individuals with obesity and 18 (0.34%) individuals with normal weight, among 9771 individuals (5223 with normal weight and 4548 with obesity)." (PMID 41596694, 2026). "Our meta-analysis indicates that rare coding variants in MRAP2 were associated with higher odds of obesity, consistent with findings in a mouse model where Mrap2−/− mice exhibit early-onset severe obesity." (PMID 41596694, 2026). "Since the MRAP2 R125C variant was reported in four studies, we further analyzed the relationship between this mutation and obesity." (PMID 41596694, 2026). "Using inverse-variance–weighted random-effects models fitted with restricted maximum likelihood, carriers of rare coding MRAP2 variants had higher odds of obesity (OR = 2.61; 95% CI, 1.49–4.58; p = 8.0 × 10−4)." (PMID 41596694, 2026). "MRAP2 coding variants were identified in 64 (0.91%) subjects with obesity or overweight and 18 (0.34%) individuals with normal weight." (PMID 41596694, 2026). "In summary, this systematic review and meta-analysis indicates that rare coding variants in MRAP2 are associated with higher odds of obesity in the currently available observational studies." (PMID 41596694, 2026). "To address this gap, we conducted a comprehensive systematic review and cohort-level meta-analysis to quantify the association between rare coding variants in MRAP2 and obesity." (PMID 41596694, 2026). "This is the first meta-analysis to investigate the association between MRAP2 variants and obesity across various ethnic populations." (PMID 41596694, 2026). "Functional effects of five obesity-associated MRAP2 variants were analysed in HEK293 cells by co-expressing wild-type or variant MRAP2 with MC4R or GHSR." (PMID 41758604, 2026). "Although rare MRAP2 variants have been reported in obese individuals, their overall impact on human obesity risk remains uncertain because previous studies were small, heterogeneous, and often lacked systematic functional characterization." (PMID 41596694, 2026). "Human mutations in MRAP2 cause obesity with hyperglycaemia and hypertension, suggesting that its regulation of GPCRs is critical for maintaining metabolic homeostasis." (PMID 41040264, 2025). "In summary, our studies demonstrate that human MRAP2 variants associated with obesity impair multiple MC4R signaling pathways and that both Gs-cAMP and Gq-IP3 pathways should be assessed to determine variant pathogenicity." (PMID 39807633, 2025). "Our studies have demonstrated that MRAP2 variants associated with human obesity impair multiple aspects of MC4R signaling." (PMID 39807633, 2025). "In summary, our studies demonstrate that human MRAP2 variants that are associated with obesity impair MC4R signaling by affecting multiple signaling pathways." (PMID 39807633, 2025). "Deletion of the MRAP2 gene from mice on various genetic backgrounds is associated with extreme obesity, increased fat mass and visceral adiposity, analogous to MC4R knockout mice." (PMID 41401256, 2025). "Twenty-six missense variants in the MRAP2 gene have been reported in individuals or families with overweight and/or obesity, although only a subset have been shown to be functionally damaging." (PMID 39807633, 2025). "Genetic variants in MRAP2 associated with overweight or obesity modulate the constitutive activity of all three GPCRs." (PMID 41040264, 2025). "Deletion of the MRAP2 gene from mice on a variety of genetic backgrounds is associated with extreme obesity, increased fat mass and visceral adiposity, analogous to MC4R knockout mice." (PMID 39574659, 2024). "Previous studies have identified associations between MRAP2 genetic variants and obesity, hypertension and diabetes." (PMID 39574659, 2024).
Obesity (continued). "The expression of SERPINA12 was positively correlated with obesity and insulin sensitivity, while mutations in MRAP2 were significantly associated with increased obesity risk." (PMID 38676834, 2024). "Global and Mc4r neuron-specific inactivation of MRAP2 increased food intake, weight gain and adiposity, and inactivating human MRAP2 variants have been identified in patients with hyperphagic obesity with hyperglycaemia and hypertension." (PMID 36943057, 2023). "Here, we find that the central mechanism of MRAP2-associated obesity is the critical role for MRAP2 in targeting MC4R to cilia." (PMID 36692018, 2023). "Mrap2-deficient mice develop severe obesity, and many MRAP2 variants have been found in severely obese human patients." (PMID 36077245, 2022). "Melanocortin Receptor Accessory Protein 2 (MRAP2) is an important regulator of energy homeostasis and its loss leads to severe obesity in rodents." (PMID 35207461, 2022). "The global deletion of MRAP2 in mice and loss‐of‐function variants in humans developed severe obesity syndrome." (PMID 36314066, 2022). "MRAP2-deficient mice develop severe obesity, which is presumably resulting from a significant decrease in MC4R sensitivity to α-MSH in the absence of MRAP2 protein." (PMID 35741395, 2022). "We characterized the obesity-associated MRAP2 mutants R125H and R125C in terms of regulation of PKR2 activity." (PMID 36077245, 2022). "The role of MRAP2 in melanin signaling is unclear, but loss-of-function MRAP2 variants are associated with obesity, which also involves α-MSH, Mc1R, and MC4R signaling." (PMID 34436011, 2021). "This gene would play a role in growth, as well as another candidate, MRAP2, which modulates melanocortin receptor signaling and have been associated with severe obesity in human." (PMID 34925440, 2021). "Food intake drives obesity in strains deficient for melanocortin 2 receptor accessory protein 2, Mrap2-/-, carboxypeptidase E, Cpe-/-, proprotein convertase 1, Pcsk1+/-, or growth differentiation factor 15, Gdf15-/-." (PMID 32356724, 2020). "Although MRAP2 has been shown to regulates a number of GPCRs involved in metabolism, the key neurons responsible for the phenotype of gross obesity in MRAP2 deficient animals are unclear." (PMID 30352741, 2018). "To identify the cause of the obesity phenotype, we investigated how deleting MRAP2 impacts energy homeostasis in 11- to 13-week-old mice." (PMID 28959025, 2017). "Mice with global and brain-specific Mrap2 deletion developed marked obesity and rare loss-of-function or missense heterozygous variants in MRAP2 were also identified in humans with severe early-onset obesity." (PMID 27106110, 2016). "Taken together, our study points towards the likelihood of MC4R-independent mechanisms and possibly MCR-independent pathways in the pathogenesis of MRAP2-associated obesity." (PMID 27106110, 2016). "The Melanocortin Receptor Accessory Protein 2 (MRAP2) is an important regulator of energy homeostasis and its loss causes severe obesity in rodents." (PMID 26829592, 2016). "In comparison, genetic screening of two large obese pediatric cohorts identified only four rare heterozygous MRAP2 variants (N88Y, L115V, R125C, E24X) in patients with severe early onset obesity." (PMID 26113808, 2015). "The role of its paralog melanocortin-2-receptor accessory protein 2 (MRAP2), which is predominantly expressed in the hypothalamus including the paraventricular nucleus, has recently been linked to mammalian obesity." (PMID 26113808, 2015). "A recent publication describing obesity in rodents and humans with MRAP2 deficiency has demonstrated that this is indeed the case." (PMID 26113808, 2015). "Therefore, this systematic review and meta-analysis aim to comprehensively evaluate the relationship between genetic variants in the coding region of MRAP2 and the risk of obesity across multiple population-based studies." (PMID 41596694, 2026).
Obesity (continued). "In vitro functional assays on MRAP2 variants support its involvement in obesity pathogenesis." (PMID 41596694, 2026). "Loss-of-function pathogenic variants in MRAP2 are related to monogenic hyperphagic obesity associated with hyperglycemia and hypertension, contrasting with the other monogenic forms of obesity that present generally with low blood pressure and normal glucose tolerance." (PMID 40822950, 2025). "MRAP2 genetic variants are associated with obesity, hypertension and diabetes." (PMID 41401256, 2025). "Human MRAP2 genetic variants reported in studies of overweight and obesity." (PMID 39807633, 2025). "The first study to functionally assess three MRAP2 variants identified in children with extreme obesity, showed only one variant affected MC4R-generated cAMP responses, although only a single concentration (1 μM) of αMSH was used in an endpoint assay (AlphaScreen)." (PMID 39807633, 2025). "Furthermore, monoallelic, pathogenic mutations in MRAP2 cause monogenic obesity associated with metabolic syndrome in humans." (PMID 39237720, 2025). "Enrichment of MC4R in cilia requires its interaction partner, the single pass membrane protein melanocortin receptor accessory protein 2 (MRAP2) and deletion of MRAP2 or mutations that block ciliary targeting of MC4R result in profound obesity in human patients and in mice." (PMID 39899600, 2025). "Human mutations in MC4R and MRAP2 are associated with obesity." (PMID 41401256, 2025). "Similarly to MC4R, human genetic variants in MRAP2 have been identified in several families and individuals with obesity that reduce MC4R activity." (PMID 41401256, 2025). "Mutations in C40 have been reported in individuals with obesity, and we predict that MRAP2 interactions with C40 could be important in maintaining the structural integrity of the MRAP2-MC4R-Gs bound state." (PMID 39807633, 2025). "Genetic variations can also lead to obesity: example, a rare and likely pathogenic MRAP2 variant (potentially deleterious effect in MRAP2) and some POMC variants (2 mutations predicted to impair protein function) existed in a cohort of severely obese Brazilian adults." (PMID 40186666, 2025). "As deficiency in MRAP2 partly affects the MC4R pathway, the subsequent energy homeostasis dysregulation and obesity in MRAP2-deficient subjects might be theoretically improved by an MC4R-agonist treatment." (PMID 40822950, 2025). "Several studies have described heterozygous MRAP2 variants in association with human obesity." (PMID 39807633, 2025). "Mutations in MRAP2 are linked to obesity and metabolic disorders." (PMID 39600608, 2024). "Similarly to MC4R, human genetic variants in MRAP2 have been identified in several families and individuals with obesity and reduce MC4R activity." (PMID 39574659, 2024). "Previous studies of MRAP2 in human populations identified >25 variants associated with obesity." (PMID 39574659, 2024). "Since MC4R and MRAP2 are essential for suppressing feeding behavior and since MC4R fails to localize to primary cilia in Mrap2–/– mice, it is likely that the failure of MC4R to localize to cilia accounts for the obesity observed in MRAP2-deficient mice and humans." (PMID 36692018, 2023). "In humans, MRAP2 variants were found in patients with obesity." (PMID 36692018, 2023). "Mc4rt2aCre/t2aCre Mrap2fl/fl mice fed ad libitum regular chow developed early-onset obesity with significantly higher body weight and fat mass, associated with hyperphagia compared with their Mc4rt2aCre/t2aCre Mrap2+/+ littermates." (PMID 36692018, 2023). "MRAP2 mutations are associated with severe obesity in humans." (PMID 35204745, 2022). "Human MRAP2 mutations are also associated with severe obesity." (PMID 36358958, 2022). "MRAP2 deletion or loss‐of‐function mutation resulted in obesity syndrome in mice and human." (PMID 36314066, 2022). "The mutation of MRAP2 in humans and mice also causes early-onset severe obesity." (PMID 32987823, 2020).
Obesity (continued). "MRAP2 mutations were shown to be potentially pathogenic for early-onset obesity." (PMID 32922362, 2020). "Mice deficient in Mrap2 exhibit severe obesity and a mutation in this gene may be associated with severe obesity in human patients." (PMID 33143653, 2020). "Mice deficient in MRAP2 have severe early-onset obesity due to increased fat mass." (PMID 30352741, 2018). "A mutation screen in obese children and adolescents revealed that MRAP2 variants might contribute to human obesity." (PMID 30134862, 2018). "However, we found that Mrap2 KO mice have a significant decrease in locomotor activity compared to WT littermates, suggesting that the obesity caused by MRAP2 deletion is, at least in part, due to decreased activity." (PMID 28959025, 2017). "However, importantly, obesity in Mrap2-deficient animals clearly precede any change in food intake and in paired feeding studies Mrap2-deficient animals continue to gain more weight than their wild-type counterparts." (PMID 27106110, 2016). "Loss-of-function MRAP2 mutations have also been associated with obesity in humans." (PMID 27106110, 2016). "For example, the precise mechanism of how MRAP2 causes obesity is not fully understood." (PMID 26113808, 2015). "Interestingly, a physiological role for MRAP2 in energy homeostasis was identified when loss of mouse MRAP2 function resulted in obesity." (PMID 26469516, 2015). "Rare heterozygous variants of MRAP2 have been found in humans with severe, early-onset obesity." (PMID 26113808, 2015). "Recently rare mutations in hMRAP2 have been shown to underlie the development of severe human obesity, and in vitro studies showed that this might be due to MRAP2 effects on MC4R signalling." (PMID 26469516, 2015). "This indicates that if MRAP2 mutations contribute to human obesity, they do so rarely." (PMID 26469516, 2015). "Moreover, we showed that obesity-associated MRAP2 mutations impair this effect, and consequently have increased MC4R internalization, which could explain the reductions in MC4R signaling by these MRAP2 mutant proteins." (PMID 39807633, 2025). "Indeed, variants of MRAP2 have been identified that increase the risk of obesity." (PMID 39459554, 2024). "Additionally, genetic variations in MRAP2 have been associated with obesity." (PMID 37372438, 2023). "Similarly to MRAP1, evidence for MRAP2 mutations associated with human obesity is limited." (PMID 26469516, 2015). "Moreover, the finding that MRAP2 is associated with mammalian obesity is exciting and could provide a novel therapeutic target at a time when obesity is at epidemic levels." (PMID 26113808, 2015). "Nonetheless, the results support MRAP2 as a biologically plausible candidate gene for monogenic and oligogenic forms of obesity and provide a quantitative framework for future work." (PMID 41596694, 2026). "Kinetic assays performed on cells transfected with equal concentrations of MRAP2 and MC4R show impairment of cAMP and/or IP3 signaling by the obesity-associated variants." (PMID 41401256, 2025). "Consistent with previous studies we showed that wild-type MRAP2 enhances MC4R coupling to Gs and increases cAMP signaling, and demonstrated that most obesity-associated MRAP2 variants impair cAMP signaling." (PMID 39807633, 2025). "Particularly, the physiological correlation of MRAP2 and tumors induced by obesity, hypertension, and hyperglycemia is worth to be explored in the future." (PMID 37314044, 2024). "In the study of obesity and insulin sensitivity, mutations in SERPINA12 and MRAP2 have caught our attention." (PMID 38676834, 2024). "Melanocortin-2 receptor accessory protein-2 (MRAP2) is a single transmembrane protein that interacts with MC4R to potentiate it’s signalling, and human mutations in MRAP2 cause obesity." (PMID 39574659, 2024).